IDO1 (indoleamine 2,3-dioxygenase 1)
Diseases named in the same sentence as IDO1 in open-access papers (continued):
Sharing a sentence is not in itself a finding about the gene and the disease.
tumor (continued). "Being regulated by interferons (IFNs), overexpressed IDO1 suppresses apoptosis and promotes tumour dormancy in tumour-repopulating cells (TRCs), a highly tumorigenic subpopulation of undifferentiated tumour cells." (PMID 34539663, 2021). "At the molecular level, the anti-tumor effects of curdione were mediated by indoleamine-2, 3-dioxygenase-1 (IDO1)." (PMID 33718227, 2021). "IDO1 is over-expressed in a variety of tumor cells including EC cells and immune cells such as APCs, MDSCs and macrophages." (PMID 34134781, 2021). "IDO1 suppresses the immune response in T cells by depleting Trp and accumulating Kyn in the local tumor microenvironment." (PMID 34805163, 2021). "The positive expression of IDO1 in tumor cells, intratumoral immune cells and both kinds of cells was found in 393 of 502 samples (78 %), 422 of 472 samples (89 %) and 364 (77 %) of 472 samples, respectively." (PMID 33557876, 2021). "Most clinical trials of IDO1 inhibitors have been carried out to test the anti-PD-1 antibody combination in a tumor type where anti-PD-1 antibody alone has activity." (PMID 33557876, 2021). "The key players in the depletion of arginine and tryptophan in the TME are arginase and IDO1, respectively, which have both been shown to be upregulated in tumor cells." (PMID 34948104, 2021). "IDO1 and PD-L1 have become important targets for tumor immunotherapy and multiple inhibitors have entered clinical trials and achieved certain efficacy." (PMID 34712660, 2021). "Collectively, our results are consistent with the idea that the l-1MTrp+CPA regimen is a robust therapeutic strategy for cancer immunotherapy, in which l-1MTrp blocks the tumor-derived IDO1 protein." (PMID 34148865, 2021). "Overall, these data suggest that IDO1 expression can be upregulated during tumor formation in an immunocompetent setting." (PMID 33831358, 2021). "Several tumor studies have demonstrated IDO1 upregulation that inhibits the anti-tumor activity of innate and adaptive immune cells." (PMID 34149693, 2021). "And the significant correlation was confirmed between IDO1 expression levels and the numbers of tumor-infiltrating dendritic cells and CD8+ T cells." (PMID 33536348, 2021). "Agonistic CD40 mAb treatment increased IDO1 expression in tumor endothelial cells, resulting from increased T-cell infiltration and higher levels of IFNγ in the tumor stroma." (PMID 32231867, 2020). "A significant correlation between IDO1 expression and increased FoxP3+ tumor-infiltrating lymphocytes was found in a cohort of PTMCs." (PMID 33986723, 2020). "The combination of a PD‐1 antagonist and NLG919 efficiently blocked both the PD‐L1/PD‐1 and IDO‐1 pathways, restoring the antitumor activity of CTLs to prevent tumor regression." (PMID 33304763, 2020). "The proportion of tumors with positive IDO1 staining was significantly higher in the group with higher levels of CD8+ TL tumor density than in the group with lower levels (65.3% vs. 12.9%, p < 0.001)." (PMID 32194552, 2020). "Taken together, our analysis suggests that IDO1 in different tumours have some special hallmarks, but they also have some common features around immune response." (PMID 32227579, 2020). "Epacadostat is the clinically most advanced IDO1 inhibitor and has been shown to inhibit tumor growth in mice models." (PMID 32153576, 2020). "In order to characterize the molecular response induced by IDO1 blockade, intratumoral biopsies—collected 13 days post tumor inoculation—were subjected to a gene expression analysis using Nanostring technology and the PanIO360 panel." (PMID 32194552, 2020). "It is challenging to deduce prognostic information of tumor cell-intrinsic Stat1 and Ido1 expression from CRC TCGA data, because both genes are expressed in neoplastic cells and immune cells." (PMID 32444775, 2020).
tumor (continued). "An overactivation and overexpression of Trp-degrading enzymes IDO1 was observed in different types of cancer, promoting tumor progression by reducing antitumor immune responses and increasing the malignant properties of cancer cells." (PMID 32957545, 2020). "A recent study found that the expression level of indoleamine 2,3-dioxygenase 1 (IDO1) was increased significantly in tumor tissues." (PMID 32756378, 2020). "In other cancers, IDO1 expression is constitutive, while tumor cells expressing IDO1 are surrounded by fewer lymphocytes." (PMID 33117713, 2020). "Combining agonistic CD40 mAb therapy with the IDO1-inhibitor epacadostat resulted in increased T-cell activation, delayed tumor growth and increased survival in B16-F10 tumors." (PMID 32231867, 2020). "Dosing of the IDO1 inhibitors was started prior to establishment of the tumor (i.e., prophylactic administration), based on previous experience of Charles River Laboratories, where the study was performed." (PMID 33584686, 2020). "Our study discovered that upregulated tumor IDO1 expression after neoadjuvant therapy was independent prognostic factor for poor prognosis in ESCC patients." (PMID 32733806, 2020). "STAT3 activation, IDO1 upregulation, and MDSC infiltration contribute to tumour-associated immune tolerance." (PMID 31819179, 2020). "In spite of the immunosuppressive action of IDO1, it has also been shown to induce inflammatory responses within the tumor microenvironment." (PMID 32486450, 2020). "IDO1 was predominantly expressed in endothelial cells within the tumor microenvironment, and its expression in tumor endothelium was positively correlated to T-cell infiltration and to increased intratumoral expression of IFNγ." (PMID 32231867, 2020). "In-depth study of the biological function of IDO1 according to the expressing (tumor) cell can help to understand if and when IDO1 inhibition can play a role in cancer therapy." (PMID 33072086, 2020). "In cancer, IDO1 can be expressed either directly by the tumor cells or induced indirectly in host antigen presenting cells by the tumor." (PMID 32637034, 2020). "The apparent inflammation-induced IDO1 expression in these patients probably indicates a stronger innate anti-tumor immune response." (PMID 32153576, 2020). "Riesenberg et al28 investigated that the immunogenic RCC tumours especially benefit from the presence of IDO1." (PMID 32227579, 2020). "It was demonstrated that both IDO protein expression and function were reduced and tumor progression was significantly delayed when epacadostat, a known IDO-1 inhibitor, was used." (PMID 33375686, 2020). "Clinicopathological features and the changes of tumor IDO1 expression and CD8+TILs density after neoadjuvant therapy." (PMID 32733806, 2020). "IDO1 can also be expressed by other cells in the tumor microenvironment, including dendritic cells and vascular endothelial cells." (PMID 33363543, 2020). "By co-opting IDO1 activity, tumor cells can mask their rapid cellular growth effectively and evade the host immune response." (PMID 33007982, 2020). "As a pivotal contributor to immunosuppression, higher IDO1 expression at the tumor invasion front is involved in CRC progression, and it has been found to correlate with impaired clinical outcomes." (PMID 33425745, 2020). "IDO1 expression was specifically increased in the tumor endothelial pool following anti-CD40 treatment of B16-F10 tumors, whereas it was almost undetectable in the unbound fraction." (PMID 32231867, 2020). "Additional research into the role of the IDO1 pathway in the maintenance of tumour microenvironment is necessary for further development of IDO1 inhibitors." (PMID 31124055, 2020). "Trp catabolism through increased IDO1 activity enables cancer progression by suppressing anti-tumour immune responses." (PMID 31819194, 2020).
tumor (continued). "With the growing relevance of the kynurenine pathway to various aspects of tumor biology, development of inhibitors targeting this pathway has increased with a focus on IDO1 and TDO." (PMID 32824193, 2020). "Indole-2,3-dioxygenase 1 (commonly referred to as IDO or IDO1) is a key enzyme in tryptophan catabolism and in tumors, high IDO1 levels derived from tumor cells and tolerogenic myeloid cells leads to the inhibition of effector T cells and NK cells." (PMID 33013886, 2020). "The IDO1+ tumor cells were arranged in an alternating pattern with IDO1− tumor cells in neoplastic adenoma sheets." (PMID 32444775, 2020). "Agonistic CD40 mAb treatment substantially increased the expression of IFNγ and IDO1 in tumor tissue, and their levels in individual tumors were positively correlated." (PMID 32231867, 2020). "Due to its role in tumour immunosuppression, IDO1 represents an attractive target for cancer therapy." (PMID 31124055, 2020). "Ido1 has therefore been overexpressed in murine cancer cells to investigate its in vivo functions, or ablated from mice to investigate the effect of host Ido1 on tumour development and progression." (PMID 31819194, 2020). "IDO1 is produced in mesenchymal stromal cells, endothelial cells, fibroblasts, tolerogenic DCs, TAMs, CAFs, MDSCs, and elevated in tumor cells and can be loaded into tumor-derived microvesicles." (PMID 32499786, 2020). "Firstly, the IDO1 expression level in TCGA database was only detected by next gene sequencing using the whole RNA extracted from tumours which contained both tumour cells (TCs) and tumour‐infiltrating cells (TILs)." (PMID 32227579, 2020). "Stratification of patients for IDO1 inhibitor treatment based on IDO1 expression and activity (based on Trp and Trp-derived metabolites, such as Kyn and Kyn catabolite levels) in the tumour tissues and body fluids therefore is critical." (PMID 31819194, 2020). "Stimuli produced by the anti-tumor response, such as IFNγ, are likely to induce contemporaneous expression of IDO1, IL4I1, and iNOS, with still undetermined consequences." (PMID 33392202, 2020). "The IDO pathway is also immunomodulatory, with IDO1 well-characterized as a mediator of tumor immune evasion." (PMID 32973768, 2020). "Given the important role in tumor immune escape, IDO1 represents a valuable therapeutic target in cancer immunotherapy." (PMID 33007982, 2020). "We observed that IDO1, IL20RB, PPP3CA, and PLAU were negatively associated with favorable outcomes and were found to participate in tumor progression, whereas ESR2 showed the opposite effect." (PMID 33718118, 2020). "Numerous studies have supported the notion that IDO1-mediated Trp catabolism promotes tumour progression, thus making IDO1 inhibitors attractive targets for clinical development." (PMID 31819194, 2020). "IDO1 promotes an inflammatory protumorigenic environment and contributes extensively to neovascularization, which is essential for tumor growth and the formation of metastases." (PMID 33374836, 2020). "In cancers, increased IDO1 activity has been shown to promote the development of an immunosuppressive microenvironment and inhibit anti-tumor immune responses." (PMID 32486450, 2020). "About 50% of IDO1+ tumor cells were Lysozyme-positive, demonstrating a significant contribution of Paneth cells to Ido1 expression in the neoplastic epithelium." (PMID 32444775, 2020). "IDO1 is expressed in multiple tumour types, including melanoma, pancreatic adenocarcinoma, ovarian cancer, acute myeloid leukaemia, colorectal cancer, prostate cancer and endometrial cancer." (PMID 31124055, 2020). "IDO1 is also involved in promoting tumor neovascularization by modulating the expression of interferon-γ (IFN-γ) and IL-6." (PMID 32486450, 2020). "Compared with pre-infusion tumor tissues, post-CAR-T cell infusion tumor specimens show markedly upregulated expression of many immunosuppressive molecules, particularly IDO1 and Foxp3, and in some cases, IL-10, PD-L1, and/or TGF-β." (PMID 32117960, 2020).
tumor (continued). "The increase in IDO1 in B16-F10 tumor endothelial cells treated with agonistic CD40 mAb correlated with IFNγ expression in the tumor tissue." (PMID 32231867, 2020). "We analyzed the relationship between clinicopathological features and the changes of tumor IDO1 expression and CD8+TILs density among 85 patients." (PMID 32733806, 2020). "Then tumor volume was measured, and the tumor tissue was formalin fixed and used for immunohistochemical staining to detect the protein expression of IDO1 and GBP1." (PMID 33552086, 2020). "The overall proportion of PD-L1+ cells is also higher than IDO-1+ cells in the tumor tissue, indicating variation between the expression of these two molecules on macrophages." (PMID 32260340, 2020). "Overall, compound i12 is a potent lead compound for developing IDO1 inhibitors and anti-tumor agents." (PMID 32210078, 2020). "An IDO1/AhR inhibitor reversed the tumor dormancy response and resulted in reduced spheroid growth after exposure to IFNγ in vitro." (PMID 33379189, 2020). "Tumor repopulating cells (TRCs), a self-renewing, highly tumorigenic subpopulation of cancer cells, highly express IDO1 and transfer kynurenine to CD8+ T cells, which induces programmed cell death protein 1 (PD-1) expression through the kynurenine-AhR pathway." (PMID 32824193, 2020). "The oncogenic function of Ido1 in CAC was attributed to tumor cell-intrinsic phosphatidylinositol-3-kinase–Akt-mediated nuclear translocation of β-catenin rather than immunosuppression." (PMID 32444775, 2020). "These analyses revealed protein expression of Paneth cell markers Lysozyme and MMP7 in IDO1+ tumor cells." (PMID 32444775, 2020). "Together, these results indicate that inhibition of IDO1, mainly expressed in tumor endothelial cells, reduced expression of immunosuppressive molecules associated with T-cell exhaustion during agonistic CD40 mAb therapy." (PMID 32231867, 2020). "Our previous study demonstrated that treatment with short-hairpin RNA against Ido1 (IDO shRNA) suppresses tumor growth, detects Th1-bias immune responses, and elevates expression of tryptophan transfer RNA (tRNATrp) in total splenocytes." (PMID 32933162, 2020). "Indoximod has been demonstrated to have a stronger anti-tumor effect in some studies compared to its L-isomer even though it is a very weak inhibitor of IDO1." (PMID 32469935, 2020). "This is the first study analyzed the relationship between the changes of tumor IDO1 expression after neoadjuvant therapy (including NCRT and NCT) and prognosis in ESCC." (PMID 32733806, 2020). "Overexpression of IDO1 gene contributes to the depletion of local trp and to the elevation of kyn in the tumour microenvironment that makes it immunosuppressive." (PMID 32776284, 2020). "Indoleamine 2,3-dioxygenase 1 (IDO1) as a key rate-limiting enzyme in the kynurenine pathway of tryptophan metabolism plays an important role in tumour immune escape." (PMID 32466694, 2020). "Meanwhile, the immunosuppressive tumor microenvironment (ITM) is reversed by NLG919‐mediated IDO‐1 inhibition." (PMID 32328426, 2020). "Indoleamine-pyrrole 2,3-dioxygenase 1 (IDO-1) is a heme-containing enzyme physiologically expressed in many tissues and cells, which is activated during tumour development, helping malignant cells escape eradication by the immune system." (PMID 33023131, 2020). "Second, as within the tumor, inhibitory regulatory molecules such as PD-L1, PD-L2, galectin-9, indoleamine 2,3-dioxygenase 1 (IDO-1), and human B7 homolog 3 (B7-H3) can be upregulated on vascular endothelial cells to directly inhibit T cell activity." (PMID 33614478, 2020). "This can further confirm that astragaloside IV blocks the extracellular localization of IDO1 to enhance the anti-tumor effect of PD-1 inhibitors." (PMID 33552086, 2020). "To further examine the expression of PD-L1 and IDO-1 proteins in the tumor tissue, and particularly in TAMs, we profiled the cellular immunophenotypes with antibody-based mIHC." (PMID 32260340, 2020).
tumor (continued). "Noteworthy are in particular two markers (ARG1 and IDO1) that cooperate to establish an immunosuppressive tumor microenvironment." (PMID 31960110, 2020). "Since activation of T-cells is associated with enhanced IFNγ production, we investigated if IDO1-expression in tumor endothelial cells in response to agonistic CD40 mAb immunotherapy was related to increased infiltration of activated T-cells." (PMID 32231867, 2020). "By contrast, HNSCC samples presented with IDO1 but only on a small fraction of tumor-infiltrating lymphocytes." (PMID 32117235, 2020). "Tumor IDO1 expression was evaluated and compared between endoscopically biopsied tissue samples and surgical specimens." (PMID 32733806, 2020). "More than 80% of IDO1+ tumor cells expressed Paneth markers, indicating that Paneth cells are the major source for Ido1 expression in the neoplastic epithelium." (PMID 32444775, 2020). "In a similar vein, there has been a major effort to develop inhibitors of IDO1 to prevent the immune-suppressant activity of this enzyme and thus to drive tumor cell death or to facilitate the effects of anti-tumor drugs." (PMID 32194572, 2020). "Despite the high proportion of CD8 T cells in the tumor microenvironment, tumor cells can still escape from immunology attack due to the immunosuppressive function of IDO1." (PMID 33425745, 2020). "It is reported that indoleamine-pyrrole 2,3-dioxygenase (IDO1) is an effective immunosuppressive enzyme, which is upregulated in EBVaGC to resist tumor immune responses." (PMID 33381453, 2020). "We previously demonstrated that IDO1 has an important role in thyroid carcinogenesis inducing an immunosuppressant tumor microenvironment." (PMID 31936153, 2020). "In CRC, IDO1 expression at the tumor invasion front correlates with disease progression and worse clinical outcome and is associated with the frequency of liver metastases." (PMID 33178611, 2020). "Low-level IDO1 production in the tumor microenvironment contributes to this tumor defense by inhibiting tumor proliferation." (PMID 32153576, 2020). "Correlations between IDO2 expression, clinical-pathological data, tumor-infiltrating lymphocytes (TILs), immunosuppressive tumor molecules (IDO1 and programmed cell death ligand-1 – PD-L1 –) and patients' prognosis were evaluated." (PMID 32536910, 2020). "In one of the GSE10878 data set, IDO1 overexpression was seen in tumor tissue compared to normal brain (Log2FC = 0.88, p = 0.024), but fold change >2 was not reached." (PMID 32469935, 2020). "The design and development of potent and selective inhibitors of the catalytic activity of IDO1 have so far represented the major goal of medicinal chemists in order to enhance anti-tumor immune responses." (PMID 33584695, 2020). "The adenosine-AR signals in dendritic cells upregulate IL-10, IDO-1, TGFβ, and arginase-2, thus facilitating naïve T-cell differentiation toward Th2 lineages and promoting tumor growth." (PMID 32775303, 2020). "These seem to indicate that inhibiting the activity of IDO1 can enhance the anti-tumor effect of PD-1 inhibitors." (PMID 33552086, 2020). "IDO1 activity inhibits T-cell activation and proliferation and even mediates regulatory T-cell recruitment to the tumor microenvironment, provoking local immune tolerance." (PMID 32117235, 2020). "Considering that the existing studies have proved the anti-tumor effect of astragaloside IV, we selected astragaloside IV as a candidate interface inhibitor for IDO1 and GBP1." (PMID 33552086, 2020). "We revealed that IDO1 was significantly up‐regulated in all of the female tumours according to TCGA database." (PMID 32227579, 2020). "It is demonstrated that depletion of IDO1 can suppress T-cell function and elevate expression of IDO1 in a tumor, which is correlated with poor prognosis in GBM patients." (PMID 33767690, 2020). "Tumours with high IDO1 deplete the essential amino acid tryptophan from TME, resulting in T-cell anergy and immune suppression." (PMID 33023131, 2020).